POSTN (periostin)
Diseases named in the same sentence as POSTN in open-access papers (continued):
Sharing a sentence is not in itself a finding about the gene and the disease.
cardiac hypertrophy (continued). "Similarly, periostin (POSTN), another DEG with >8 FC in the current results, also appears to be a target for reversing the impact of cardiac hypertrophy via the NFAT pathway." (PMID 26207811, 2015). "Analysis of 11β-HSD1 inhibition in the Isoproterenol-induced model yielded similar results by restoring normal levels of expression of ANP (another marker of cardiac hypertrophy and periostin but not of Glut1." (PMID 24667808, 2014). "If periostin expression is exhausted and/or not adequate, the tissue/organ may fail to remodel appropriately, leading to an insufficient response (e.g., mice with cardiac hypertrophy)." (PMID 24146092, 2014).
metastatic tumors (19 papers, 2006 to 2025). "Clinical studies have demonstrated that periostin upregulation (or elevated circulating levels of periostin) is associated with an increased metastatic tumor burden and a poor patient prognosis." (PMID 37716956, 2023). "The elevated expression of fibronectin and periostin was also associated with the source of ovarian tumor sample: more samples with a higher expression of these proteins were among samples derived from omental metastatic disease than among other samples." (PMID 31936272, 2020). "Intriguingly, POSTN demonstrated a marked elevation in liver metastatic tumors compared to primary tumors." (PMID 39762921, 2025). "This evidence would support the use of periostin as a single marker to monitor disease progression in patients subjected to radical treatments or receiving systemic therapy for metastatic disease, an aspect that deserves validation in future studies." (PMID 35887333, 2022). "POSTN has also been discovered in cancer-derived exosomes and was enriched in exosomes secreted from metastatic tumor cells and in plasma samples from patients with LN metastasis." (PMID 35567669, 2022). "Increased POSTN expression in the stroma surrounding primary and metastatic tumors or in the serum of patients with malignant tumors is considered a negative prognostic biomarker." (PMID 33919736, 2021). "We observed more tumors with stronger periostin expression (score 2 or 3) among the samples derived from omental metastatic disease (P) than in remaining samples (53% & 8% vs. 29% & 5%; χ2 test, p = 0.032)." (PMID 31936272, 2020). "Examination of the size and number of primary and metastatic tumor lesions revealed that the primary tumors were smaller in periostin−/− mice (2,947 ± 544.5 mm3) than in periostin+/+ mice (5,656 ± 461 mm3)." (PMID 30131847, 2018). "The over-expression of Periostin, a member of the fasciclin family of proteins, has been reported in a number of cancers and, in particular, in metastatic tumours." (PMID 26543579, 2015). "POSTN overexpression in metastatic tumors was confirmed by an analysis of 19 hepatic metastases from intraocular melanoma (P = 0.002)." (PMID 18086302, 2007). "As metastatic tumors are usually much more resistant to chemotherapy, we can suppose that periostin could also play a role in the drug resistance of metastatic tumors, such as in the case of drug-resistant cell lines." (PMID 31412536, 2019). "In HNCs, the CAF-derived POSTN directly accelerated cancer cell proliferation, migration and invasion and indirectly modulated a tumor-supportive microenvironment in the primary and metastatic tumors, thereby resulting in the colonization initiation and metastasis of the tumor." (PMID 26857387, 2016). "We found six genes such as SPP1, VEGFA, POSTN, RUNX2, CD44, and FOXO1 that were consistently overexpressed in patients with bone metastasis compared to non-metastatic tumors." (PMID 36424413, 2022).
allergic rhinitis (18 papers, 2015 to 2026). Inflammation of the nasal mucous membranes caused by an IgE-mediated response to external allergens. "The study was the first to compare the levels of periostin in the nasal secretion of children with atopic bronchial asthma and various clinical forms of allergic rhinitis." (PMID 34796003, 2021). "In the part of allergic rhinitis (AR), in comparison with normal nasal tissues, periostin levels significantly increased in the basement membranes of AR patients." (PMID 32954441, 2021). "Both blood and saliva AREG levels showed positive correlations with allergic rhinitis status, atopy status, eczema status, plasma periostin, neutrophilia, Montelukast sodium use, ACT score, FEV1, and FEV1/FVC." (PMID 33195308, 2020). "Quercetin suppressed the production and function of periostin in human nasal epithelial cells and resulted in improvement of clinical conditions of allergic rhinitis." (PMID 27034956, 2016). "Periostin in nasal secretions of patients with different clinical courses of allergic rhinitis." (PMID 34796003, 2021). "However, the significance of periostin as a biomarker of local allergic inflammation in the nasal mucosa (NM) of patients with atopic bronchial asthma (BA) and allergic rhinitis (AR) is yet to be determined." (PMID 34796003, 2021). "There are other allergic conditions, such as allergic rhinitis, in which no elevation of periostin level in the serum could be found." (PMID 34512647, 2021).
osteosarcoma (18 papers, 2007 to 2025). A usually aggressive malignant bone-forming mesenchymal neoplasm, predominantly affecting adolescents and young adults. "A multivariate analysis confirmed that POSTN overexpression was an independent risk factor for prognosis in patients with osteosarcoma." (PMID 35832544, 2022). "A study on osteosarcoma has implied that POSTN overexpression is associated with tumor angiogenesis and poor prognosis." (PMID 35832544, 2022). "Increased levels of periostin have been associated with tumour angiogenesis, metastatic potential and poor prognosis in osteosarcoma patients." (PMID 30202513, 2018). "For instance, low levels of periostin has been associated to high levels of Erk phosphorylation in lysophosphatidic acid-treated osteosarcoma cells." (PMID 26809067, 2016). "Moreover, high expression of POSTN (periostin, also known as osteoblast-specific factor two) in osteosarcoma is significantly associated with angiogenesis and is considered to be a promising prognostic factor in osteosarcoma patients." (PMID 32582282, 2020). "While these results support a role for periostin in Th2-associated bone remodeling, the physiological generalizability is limited by the use of MG63 cells, which are derived from osteosarcoma cell lines." (PMID 40607434, 2025). "Among the top DEPs identifying fibroblastic groups from other pathological subtypes are POSTN, TPM4, RTN4, HNRNPK, and RACK1, which were directly associated with osteosarcoma progression and prognosis." (PMID 37681913, 2023). "At first, the mouse periostin cDNA was used as a probe to screen human placental and osteosarcoma cDNA libraries." (PMID 36224629, 2022). "In humans, the ORF of placental periostin encodes an 87 kDa protein with 779 amino acids, whereas the ORF of osteosarcoma periostin encodes a 93.3 kDa protein with 836 amino acids and 838 amino acids in mice." (PMID 36224629, 2022). "Expression of periostin in osteosarcoma has previously been reported with high expression being correlated with tumour angiogenesis and poor prognosis." (PMID 30202513, 2018). "The histopathological and immunohistochemically analysis showed that POSTN expression was higher in osteosarcoma than in osteochondroma and correlated with VEGF expression, histological subtype, and tumor size." (PMID 29946533, 2018). "Previous research proved that POSTN played crucial roles in bone metastasis and osteosarcoma." (PMID 39947253, 2025). "It was found that POSTN may have an essential role in tumor progression and may be used as a prognostic biomarker for patients with osteosarcoma." (PMID 37681913, 2023). "In osteosarcoma, there was strong staining for periostin in the osteoid matrix formed by malignant cells; staining for periostin was seen in all osteosarcomas but the extent of expression was variable with osteoid-rich tumours showing the strongest and most diffuse staining." (PMID 30202513, 2018). "A similar pattern of staining for periostin was noted in lung nodules of metastatic osteosarcoma." (PMID 30202513, 2018). "In small cell osteosarcoma, periostin was expressed in the matrix between tumor cells." (PMID 30202513, 2018). "Furthermore, POSTN exhibited a significantly higher expression in osteosarcoma than normal tissues." (PMID 35578666, 2022). "However, the effect of POSTN on the progression, proliferation, and invasion of osteosarcoma (OS) remain unclear." (PMID 35057799, 2022). "Meanwhile, some hub genes have been reported involved in the tumorigenesis and progression of osteosarcoma, such as ITGAV, POSTN, COL1A1, TGFB1, TGFB3, and ITGAV." (PMID 32582282, 2020). "Periostin has been identified in a few bone tumours, including fibrous dysplasia and osteosarcoma, but its expression in other bone neoplasms has not been fully investigated." (PMID 30202513, 2018).
chronic kidney disease (17 papers, 2012 to 2025). Impairment of the renal function secondary to chronic kidney damage persisting for three or more months. "Previous reports suggested that periostin performs a crucial role in fibrosis, and acute kidney injury resulting in a high risk of progression to chronic kidney disease." (PMID 36359784, 2022). "Whether periostin is implicated in hypertensive nephropathy and in the progression/reversal of chronic kidney disease remained unknown." (PMID 22403621, 2012). "Anti-Periostin antibodies were able to significantly reduce fibrosis in chronic kidney disease in the cell culture of a mouse model by altering inflammatory and TGFβ signalling pathways." (PMID 39940700, 2025). "Periostin is a matricellular protein, which is de novo expressed during the development of renal disease and is a target of therapy in chronic renal disease (CKD)." (PMID 38039285, 2023). "A recently published study showed that periostin is induced by proinflammatory factors, mainly NFκB in a model of chronic renal disease, and that inhibition of periostin can be used as a therapeutic strategy to slow down renal disease progression." (PMID 31726998, 2019). "AOs were utilized to inhibit periostin in an NG-nitro-l-arginine methyl ester hydrochloride (l-NAME)-induced rat model of chronic kidney disease (CKD), with treated rats showing reduce fibrosis and tubular dilation." (PMID 29941814, 2018). "Periostin is a marker of renal tubular injury and related to progressive kidney injury in animal models of chronic kidney disease." (PMID 25884625, 2015). "Further research is necessary to precise the potential of renal, plasma and urine periostin as prognostic biomarkers to monitor the progression and therapeutic control of human chronic kidney diseases." (PMID 22403621, 2012). "Emerging data indicate periostin as a novel marker and mediator of chronic kidney disease CKD." (PMID 35883655, 2022). "Furthermore, an upregulated periostin expression was observed in calcifying dermal fibroblasts, calcified human aortic valves, atherosclerotic plaques and left ventricular tissues of rats with chronic renal failure." (PMID 36009051, 2022). "Recent studies have demonstrated that periostin was excreted in the urine of experimental animal models of chronic kidney disease (CKD) and patients with various kidney diseases including chronic allograft nephropathy (CAN)." (PMID 25884625, 2015). "One study showed that POSTN promotes cell proliferation and macrophage polarization to drive tissue repair after acute kidney injury, and POSTN was found to contribute to renal and cardiac dysfunction in rats with chronic kidney disease (CKD)." (PMID 33488671, 2020).
systemic sclerosis (16 papers, 2012 to 2025). A chronic disorder, possibly autoimmune, marked by excessive production of collagen which results in hardening and thickening of body tissues. "In conclusion, combining N-terminal prohormone brain natriuretic peptide, periostin, and galectin-3 as serum biomarkers enhances risk stratification and sensitivity in detection of cardiac disease in patients with systemic sclerosis." (PMID 40743121, 2025). "Overexpression of periostin has also been described in hypertrophic scar and keloid formation and linked to the pathogenesis of skin fibrosis in systemic sclerosis." (PMID 31288483, 2019). "The results of our subgroup analyses suggest that periostin is worth of further investigation as a potential biomarker of specific RDs, i.e. rheumatoid arthritis and systemic sclerosis." (PMID 40053143, 2025). "In conclusion, our study has shown the presence of significant elevations in circulating periostin, a protein modulating inflammation, angiogenesis, and fibrosis, in specific types of RDs, i.e. rheumatoid arthritis and systemic sclerosis." (PMID 40053143, 2025). "Significant elevations in periostin concentrations were observed in studies of patients with rheumatoid arthritis and systemic sclerosis." (PMID 40053143, 2025). "Pending additional studies, these observations support the proposition that the upregulation of periostin can directly or indirectly favour dysregulated inflammation, angiogenesis, and fibrosis, commonly observed in rheumatoid arthritis and systemic sclerosis." (PMID 40053143, 2025). "Elevated levels of periostin have been associated with certain types of cancers, lung diseases, such as idiopathic pulmonary fibrosis and asthma, and skin diseases, such as atopic dermatitis (AD) and systemic sclerosis (SSc)." (PMID 39453476, 2024). "Enhanced circulating blood periostin levels positively correlate with disease severity in patients with systemic sclerosis (SSc)." (PMID 37531393, 2023). "To assess if periostin is elevated in SSc hearts, we investigated the periostin levels in vivo in heart samples form patients with systemic sclerosis and controls via immunofluorescence." (PMID 36369212, 2022). "Our study suggests significant periostin elevations in rheumatoid arthritis and systemic sclerosis." (PMID 40053143, 2025). "The significant elevations in periostin observed in rheumatoid arthritis and systemic sclerosis in our systematic review and meta-analysis suggest its potential utility in diagnosing these RD types, as part of a comprehensive clinical and laboratory assessment." (PMID 40053143, 2025). "Periostin is an extracellular matrix protein located in the dermis that is involved in type 2 inflammatory responses and is correlated with progressive sclerosis in systemic sclerosis." (PMID 36561717, 2022). "However, systemic sclerosis fibroblasts did highly upregulate expression of POSTN, TNC, and TIMP1." (PMID 39989459, 2025). "This study aimed to evaluate periostin serum levels and skin expression in patients with systemic sclerosis (SSc)." (PMID 38327271, 2023). "We observed that serum periostin levels in PAH/PH patients, excluding interstitial pneumonitis and systemic scleroderma patients, were still higher than in healthy controls." (PMID 35318760, 2022). "However, we observed significant periostin elevations in studies investigating systemic sclerosis and rheumatoid arthritis but not osteoarthritis." (PMID 40053143, 2025).
scleroderma (15 papers, 2012 to 2025). Scleroderma is a rare autoimmune connective tissue disorder characterized by abnormal hardening of the skin and, sometimes, other organs. "Similarly, staining of periostin, a marker linked to the tissue remodelling (which is highly expressed under fibrotic conditions and scleroderma), was also reduced in 6/7 patients." (PMID 39539991, 2024). "The POSTN gene has been reported to contribute to pathogenesis of scleroderma via PI3K/Akt-dependent mechanism." (PMID 39350339, 2024). "Lastly, immunohistochemical staining for POSTN in skin biopsy sections of scleroderma patients found POSTN expression to be entirely diffused throughout the dermis and subcutis layers." (PMID 32640520, 2020). "Using an in vivo mouse model of bleomycin-induced scleroderma, knockout of POSTN (POSTN-/- mice) provided substantial protection against dermal thickening by limiting uncontrolled collagen deposition compared to WT mice." (PMID 32640520, 2020). "To investigate the involvement of matricellular proteins in the pathogenesis of scleroderma, we focused on a novel matricellular protein, periostin, a 90-kDa, secreted, homophilic cell adhesion protein." (PMID 22911870, 2012). "To resolve this issue, we assessed the role of periostin in BLM-induced murine scleroderma using PN−/− mice." (PMID 22911870, 2012). "To assess the involvement of periostin in the pathogenesis of scleroderma, we first compared the expression of periostin in sclerotic skin lesions from scleroderma patients and skin from identical areas of healthy donors." (PMID 22911870, 2012). "Our findings also suggest that periostin directly contributes to excessive collagen synthesis in scleroderma." (PMID 22911870, 2012). "In contrast, in scleroderma lesional skin, more intense staining for periostin was observed in the surrounding ECM throughout the dermis." (PMID 22911870, 2012). "Elevated expression of periostin was observed in the lesional skin of patients with scleroderma compared with healthy donors." (PMID 22911870, 2012). "We hope that our findings will contribute to both a better understanding of scleroderma pathogenesis and the development of novel therapeutic approaches, including the possible inhibition of periostin function, for the treatment of scleroderma." (PMID 22911870, 2012). "Based on western blotting analysis and immunohistochemical staining, periostin expression was markedly elevated in lesional skin from scleroderma patients compared with skin from healthy donors." (PMID 22911870, 2012). "Additionally, a variety of other genes associated with inflammatory as well as malignant diseases were enriched in scleroderma fibroblasts (POSTN, PRSS23, TNC, and SERPINE2)." (PMID 37443817, 2023). "Periostin was upregulated in the skin of patients with scleroderma." (PMID 36611844, 2022). "Serum POSTN levels are also elevated in scleroderma as well as in pulmonary fibrosis." (PMID 30186543, 2018). "Our study is the first to assess the role of periostin in scleroderma." (PMID 22911870, 2012). "Periostin plays an essential role in the pathogenesis of Bleomycin-induced scleroderma in mice." (PMID 22911870, 2012). "Periostin may also contribute to the pathogenesis of scleroderma via the proliferation and recruitment of myofibroblasts, enhancement of Notch1 signaling, and promotion of collagen assembly." (PMID 22911870, 2012). "At present, it is unclear whether periostin is upregulated in the fibrotic lesions of scleroderma or plays a role in its pathology." (PMID 22911870, 2012). "This study was undertaken to assess the role of periostin in scleroderma." (PMID 22911870, 2012). "However, in the BLM-induced mouse scleroderma model, a reduced sclerotic response was shown in the skin of PN−/− mice, suggesting that periostin is critically involved in the pathogenesis of scleroderma." (PMID 22911870, 2012). "Furthermore, we investigated periostin−/− (PN−/−) and wild-type (WT) mice to elucidate the role of periostin in scleroderma." (PMID 22911870, 2012).